IGF2BP2 (insulin like growth factor 2 mRNA binding protein 2)
Diseases named in the same sentence as IGF2BP2 in open-access papers (continued):
Sharing a sentence is not in itself a finding about the gene and the disease.
lung cancer (26 papers, 2021 to 2026). A malignant neoplasm involving the lung. "A high expression of the IGF2BP family proteins, including IGF2BP2, showed a remarkable association with poor overall survival of patients with lung cancer." (PMID 37149646, 2023). "More importantly, lung cancer patients with higher expression of IGF2BP2 were associated with shorter overall survival and disease-free survival time in TCGA dataset." (PMID 36257938, 2022). "Overall, these results demonstrate that IGF2BP2 is upregulated and associated with poor outcomes in lung cancer." (PMID 36257938, 2022). "Moreover, aberrant IGF2BP2 expression was associated with poor overall survival (OS) in lung cancer patients." (PMID 38281999, 2024). "We demonstrated that IGF2BP2 promotes lung cancer radioresistance by forming a positive feedback loop with SLC7A5 to activate the AKT/mTOR pathway." (PMID 38281999, 2024). "Given the elevated expression of IGF2BP2 in radioresistant lung cancer cells, we further explored the specific role of IGF2BP2 in lung cancer radiosensitivity." (PMID 38281999, 2024). "In the present study, we identified a novel m6A-dependent mechanism induced by an m6A “reader” IGF2BP2 that drives lung cancer radioresistance." (PMID 38281999, 2024). "In lung cancer, Shen and colleagues demonstrated that IGF2BP2 permeates ECs in the microenvironmental via lung adenocarcinoma (LUAD) cell-derived exosomes, subsequently mediating the m6A modification of FLT4 to improve its stability and expression." (PMID 39691597, 2024). "We found that the inhibition of lung cancer tumor growth by IR was significantly enhanced when IGF2BP2 was silenced." (PMID 38281999, 2024). "We showed that inhibition of IGF2BP2 impairs radioresistance in lung cancer both in vitro and in vivo." (PMID 38281999, 2024). "In the present study, we found that the expression of IGF2BP2 is upregulated in radioresistant lung cancer cells." (PMID 38281999, 2024). "Based on TCGA lung cancer database and LUAD tissue microarray, IGF2BP2 expression was found to be elevated in lung cancer." (PMID 38281999, 2024). "Consistently, the clonogenic survival assay showed that IGF2BP2 silencing sensitized lung cancer cells to IR." (PMID 38281999, 2024). "Clonogenic survival assays, neutral comet assays, Rad51 foci formation assays, and Annexin V/propidium iodide assays were used to determine the significance of FBW7/IGF2BP2/SLC7A5 axis in lung cancer radioresistance." (PMID 38281999, 2024). "We identified IGF2BP2, an m6A “reader”, that is overexpressed in lung cancer and facilitates radioresistance." (PMID 38281999, 2024). "Bioinformatic mining was used to identify the m6A regulator IGF2BP2 involved in lung cancer radiosensitivity." (PMID 38281999, 2024). "Although different mechanisms of IGF2BP2 function have been elucidated, the specific role of IGF2BP2 in lung cancer radioresistance remains understudied." (PMID 38281999, 2024). "We unveiled a novel GLI1/SOX2OT positive loop activated by METTL3/14/IGF2BP2-modified m6A methylation to reinforce the stemness of lung cancer cells." (PMID 37149646, 2023). "Our data unveiled that GLI1 repression reversed METTL3/14/IGF2BP2 overexpression-induced proliferative advantage of lung cancer stem-like cells, suggesting its pivotal role in the whole network." (PMID 37149646, 2023). "We also found that IGF2BP2 was highly expressed in lung cancer, patients with higher IGF2BP2 indicating poor prognostic in LUAD." (PMID 37142269, 2023). "CCK8 and clonal formation assay revealed that METTL3/14 and IGF2BP2 overexpression promoted lung cancer and stem cell proliferation compared to the pENTER empty vector backbone." (PMID 37149646, 2023). "Compared with paired adjacent normal tissues, lung cancer specimens exhibited consistently upregulated METTL14/IGF2BP2/AC026356.1." (PMID 37142269, 2023). "Compared with paired adjacent normal tissues, lung cancer specimens exhibited consistently upregulated GLI1/SOX2OT/METTL3/14/IGF2BP2." (PMID 37149646, 2023).
lung cancer (continued). "Actinomycin D used to block transcription in lung cancer cells and uncover that knockdown of IGF2BP2 significantly reduced the half-life of AC026356.1 in A549 cells." (PMID 37142269, 2023). "Immunohistochemistry indicated that GLI1 and METTL3/14/IGF2BP2 were significantly upregulated in lung cancer tissues compared to those in paired normal tissues." (PMID 37149646, 2023). "Spheroid formation assay and the established histogram corroborated that GLI1 repression disrupted METTL3/14/IGF2BP2-stimulated propagation of lung cancer cells." (PMID 37149646, 2023). "A549 lung cancer cells with stable IGF2BP2 knockdown showed significantly suppressed growth, reflected by reduced tumor size and weight." (PMID 36257938, 2022). "The qPCR result confirmed that the expression of IGF2BP2 was significantly increased in lung cancer tissues compared with adjacent normal tissues." (PMID 36257938, 2022). "It was found that IGF2BP2 was widely upregulated in a variety of cancers, including head and neck, cervical and uterine, esophageal, and lung cancers." (PMID 36257938, 2022). "We next determined the biological function of IGF2BP2 and found that IGF2BP2 knockdown in lung cancer cells significantly suppressed the growth and colony formation, whereas ectopic IGF2BP2 expression moderately promoted cell growth and survival." (PMID 36257938, 2022). "We compared the expression changes (represented by log2(fold change)) of IGF2BP2 targets (i.e., 2573 transcripts) and non-IGF2BP2 targets in lung cancer cells with IGF2BP2 knockdown." (PMID 36257938, 2022). "Biologically, IGF2BP2 depletion inhibits growth and survival as well as the migration of lung cancer cells." (PMID 36257938, 2022). "Biologically, IGF2BP2 knockdown suppressed growth, colony formation and migration of lung cancer cells." (PMID 36257938, 2022). "Several miRNAs, such as miR-320b and miR-485-5p, inhibit the progression of lung cancer by targeting IGF2BP2." (PMID 36257938, 2022). "Taken together, CDC6 appears to be a direct target downstream of the LCAT1/IGF2BP2 complex for positive regulation with oncogenic potential in lung cancer cells." (PMID 36257938, 2022). "Then, we evaluated the mRNA levels of IGF2BP2 in 35 fresh lung cancer tissues and their adjacent normal tissues by qPCR." (PMID 36257938, 2022). "Through both loss-of-function (siRNA-based knockdown) and gain-of-function (ectopic overexpression) assays, we found that IGF2BP2 is a positive regulator of proliferation, colonic survival, and migration in lung cancer cells both in in vitro and in vivo." (PMID 36257938, 2022). "In lung cancer, the anti-cancer gene miR-320b downregulates the expression of IGF2BP2 and thymidine kinase 1 (TK1), thus suppressing angiogenesis and lung cancer growth." (PMID 35004679, 2021). "Similarly, IGF2BP2 promotes lung cancer radio-resistance by forming a positive feedback loop with SLC7A5, enhancing its stability and translation through m6A modification." (PMID 41522349, 2026). "Genomic amplifications creating extra copies of IGF2BP2 occur in 9% of lung cancers." (PMID 40141058, 2025). "Taken together, our study delineated a previously unknown mechanism of a positive feedback loop between IGF2BP2 and SLC7A5, and highlighted the role of the FBW7/GSK3β/IGF2BP2/SLC7A5 axis in radioresistance in lung cancer." (PMID 38281999, 2024). "Hence, these results demonstrate that FBW7 negatively regulates the stability of IGF2BP2 protein by ubiquitinating IGF2BP2 in lung cancer cells." (PMID 38281999, 2024). "m6A regulators, including METTL3, FTO, and IGF2BP2, act as tumor promoters through the C-myc pathway in an m6A-dependent manner to promote the growth, invasion, migration, and progression of various tumors, such as BC, lung cancer, and GC." (PMID 39199429, 2024). "IGF2BP2 was also found to promote tumorigenesis in lung cancer." (PMID 39095708, 2024).
lung cancer (continued). "Although it was shown that some tumor samples express lower level of IGF2BP2 than normal samples, and survival curves separate moderately, the general tendency presented in TCGA lung cancer database analyses aligned with the broadly acknowledged conclusion that IGF2BP2 acts as an oncogene." (PMID 38281999, 2024). "Our findings suggest that IGF2BP2 may be a potential therapeutic target to overcome lung cancer radioresistance, which may inform future advances in lung cancer therapy." (PMID 38281999, 2024). "We believe that SOX2OT acting as ceRNA to protect mRNA of METTL3/14/IGF2BP2 and guiding METTL3/14/IGF2BP2 to GLI1 mRNA is the pivotal mode of action of SOX2OT in GLI1 regulation since SOX2OT is located mainly in the cytoplasm of lung cancer cells (>85% in A549 and >70% in H1299 cells)." (PMID 37149646, 2023). "Indeed, in our study, IGF2BP2 was upregulated in lung tumor tissues, and its expression was highly predictive of poor prognosis for lung cancer patients." (PMID 36257938, 2022). "Of these IGF2BP2 targets, 2573 transcripts were detected in lung cancer cells." (PMID 36257938, 2022). "IGF2BP2 is overexpressed in lung cancer tissues, which is associated with poor survival of non-small cell lung cancer patients, suggesting its oncogenic role." (PMID 36257938, 2022). "We then measured the levels of CDC6 in lung cancer cells with either IGF2BP2 or LCAT1 knockdown." (PMID 36257938, 2022). "The upregulation of IGF2BP2 in lung cancer was consistently verified using different datasets." (PMID 36257938, 2022). "Taken together, IGF2BP2 is required for the growth and survival of lung cancer cells, supporting the notion that IGF2BP2 could be an attractive therapeutic target for lung cancer treatment." (PMID 36257938, 2022). "IGF2BP2 knockdown also significantly inhibited the migration capacity of lung cancer cells." (PMID 36257938, 2022). "Here, we investigated the role of IGF2BP2 in non–small-cell lung cancer (NSCLC) proliferation." (PMID 35111811, 2021). "Hence, we surmised that the FBW7/GSK3β/IGF2BP2/SLC7A5 axis may modulate lung cancer radiosensitivity." (PMID 38281999, 2024). "Finally, we determined whether the CDC6 mRNA stability is indeed affected by the knockdown of either LCAT1 or IGF2BP2 in two lung cancer cell lines." (PMID 36257938, 2022). "However, the specific role of IGF2BP2 in lung cancer remains to be investigated." (PMID 36257938, 2022). "In addition, IGF2BP2 had a promoting effect on angiogenesis in lung cancer and leiomyoma cells." (PMID 34753397, 2021). "This work expands the understanding of post-transcriptional regulation in lung cancer and identifies the RBM15/IGF2BP2-PTPRH axis as a potential therapeutic target for NSCLC intervention." (PMID 42113318, 2026). "In this study, we reveal a novel, methyltransferase‐independent role of PRMT1 in upregulating IGF2BP2 expression in HNSCC, as well as in HCC and lung cancer cells." (PMID 40270464, 2025). "We demonstrated that this positive feedback loop between IGF2BP2 and SLC7A5 promotes lung cancer radioresistance through the AKT/mTOR pathway." (PMID 38281999, 2024). "Specifically, the FBW7/GSK3β/IGF2BP2/SLC7A5 axis was characterized and shown to play a vital role in lung cancer radiosensitivity." (PMID 38281999, 2024). "Taken together, our results demonstrate that FBW7 functions alongside GSK3β to promote IGF2BP2 degradation, thus inhibiting the IGF2BP2-SLC7A5 feedback loop and impairing lung cancer radioresistance." (PMID 38281999, 2024). "HNF4G upregulates the m6A reader, IGF2BP2, by combining with its promoter region, and upregulation of IGF2BP2 enhances the thymidine kinase 1 (TK1) stability and expression, thus facilitating angiogenesis in lung cancer." (PMID 39691597, 2024). "In order to identify why IGF2BP2 overexpressed in lung cancer, we focused on FBW7 mediating IGF2BP2 ubiquitinated degradation." (PMID 38281999, 2024).
lung cancer (continued). "Overall, our study explicitly identified a positive feedback loop involving the m6A “reader” IGF2BP2 and the amino acid transporter SLC7A5 in lung cancer radioresistance." (PMID 38281999, 2024). "Here, we unveiled METTL14/IGF2BP2-mediated m6A modification of AC026356.1, which lead to its high expression in lung cancer." (PMID 37142269, 2023). "Correlation analysis indicated that the expression level of GLI1 is positively correlated to that of IGF2BP2, METTL3/14, and SOX2OT in lung cancer bulk tumor." (PMID 37149646, 2023). "Like IGF2BP2, CDC6 is also overexpressed in lung cancer tissues with poor patient survival, and CDC6 knockdown has oncogenic inhibitory activity." (PMID 36257938, 2022). "Mechanistically, the LCAT1/IGF2BP2 complex stabilized CDC6 mRNA via the m6A modification to increase the translation of CDC6, which then promoted the growth and survival of lung cancer cells." (PMID 36257938, 2022). "However, whether and how IGF2BP2 affects lung cancer cells remains to be determined." (PMID 36257938, 2022). "To this end, we thoroughly characterized CDC6 as a new m6A target of the LCAT1/IGF2BP2 complex, which promotes CDC6 expression in lung cancer cells." (PMID 36257938, 2022). "Hsa-miR-320b also inhibits lung cancer angiogenesis and tumor growth by inhibiting the hepatocyte nuclear factor 4 gamma (HNF4G) and insulin-like growth factor 2 mRNA-binding protein 2 (IGF2BP2) expression." (PMID 35958401, 2022). "Another limitation of this study was that we have not yet identified small-molecule inhibitors targeting IGF2BP2 in lung cancer therapy." (PMID 38281999, 2024). "Thus, it is feasible that there exists a correlation between the aberrant overexpression of IGF2BP2 and the relatively low activity of FBW7 in lung cancer." (PMID 38281999, 2024). "Collectively, our study revealed that the m6A “reader” IGF2BP2 promotes lung cancer radioresistance by forming a positive feedback loop with SLC7A5, suggesting that IGF2BP2 may be a potential therapeutic target to control radioresistance in lung cancer." (PMID 38281999, 2024). "Additionally, IGF2BP2 and the lncRNA-AC026356.1 positively regulated the proliferation and stemness of stem-like lung cancer cells." (PMID 37142269, 2023). "M6A-modified METTL14/IGF2BP2/AC026356.1 loop may serve as a potential therapeutic target and prognostic predictor for lung cancer therapy and diagnosis in the clinic." (PMID 37142269, 2023). "Functional analysis corroborated that GLI1 acted as a downstream target of METTL3/14/IGF2BP2, and GLI1 silencing could block the oncogenicity of lung cancer stem-like cells." (PMID 37149646, 2023). "Functional analysis corroborated that AC026356.1 acted as a downstream target of METTL14/IGF2BP2 and AC026356.1 silencing could block the oncogenicity of lung cancer stem-like cells." (PMID 37142269, 2023). "Western blotting assays confirmed that IGF2BP2 was significantly enriched in the sense-LCAT1 but not the antisense-LCAT1 pull-down fraction in both lung cancer cell lines." (PMID 36257938, 2022). "In lung cancer, the over-expressed miR-485-5p inhibits growth and invasion of cancer cells, arrests the G0/G1 cycle and disrupts the TGF-β-induced EMT by directly targeting IGF2BP2." (PMID 33568150, 2021). "Importantly, IGF2BP2 could stabilize TGFBR1 expression, thus mediating the promotion of M2 macrophage polarization and lung cancer malignant process." (PMID 39014364, 2024). "We found that IR did not affect IGF2BP2 protein level, indicating that the overexpression of IGF2BP2 in radioresistant lung cancer cells may not result from IR." (PMID 38281999, 2024). "Interestingly, IGF2BP2 targets had a significantly higher proportion of negative log2(fold change) values than non-IGF2BP2 targets, implying that knockdown of IGF2BP2 globally and preferentially inhibited the expression of IGF2BP2 target genes in lung cancer cells upon IGF2BP2 knockdown." (PMID 36257938, 2022).
lung cancer (continued). "Previously, studies have investigated the role of thirteen m6A regulatory genes in lung cancer, but the roles of seven newly discovered ones, namely, METTL16, YTHDF3, IGF2BP1, IGF2BP2, IGF2BP3, HNRNPG, and HNRNPA2B1 has not been determined." (PMID 33795529, 2021).